PSMC4 (proteasome 26S subunit, ATPase 4)
Description:
Component of the 26S proteasome, a multiprotein complex involved in the ATP-dependent degradation of ubiquitinated proteins. This complex plays a key role in the maintenance of protein homeostasis by removing misfolded or damaged proteins, which could impair cellular functions, and by removing proteins whose functions are no longer required. Therefore, the proteasome participates in numerous cellular processes, including cell cycle progression, apoptosis, or DNA damage repair. PSMC4 belongs to the heterohexameric ring of AAA (ATPases associated with diverse cellular activities) proteins that unfolds ubiquitinated target proteins that are concurrently translocated into a proteolytic chamber and degraded into peptides.
Synonyms: TBP-7; MIP224; TBP7; S6; MGC8570; MGC13687; MGC23214; RPT3
Tractability: Small molecule: an approved drug acts on it; a structure with a bound ligand is known; a high-quality ligand is known. PROTAC: ubiquitination databases record sites on it; its protein half-life has been measured; a small molecule that binds it is known.
Target class: Enzyme
Gene: Protein-coding gene on chromosome 19 (39,971,162 to 39,981,764, forward strand). Ensembl gene ENSG00000013275.
Subcellular location: Cytoplasm; Nucleus
Subcellular location (Human Protein Atlas): Cytosol; Nucleoplasm; Basal body; Mid piece; Principal piece; Vesicles
Pathways (Reactome):
Immune System: AMPK-induced ERAD and lysosome mediated degradation of PD-L1(CD274); Activation of NF-kappaB in B cells; Antigen processing: Ubiquitination & Proteasome degradation; CLEC7A (Dectin-1) signaling; Cross-presentation of soluble exogenous antigens (endosomes); Dectin-1 mediated noncanonical NF-kB signaling; Downstream TCR signaling; ER-Phagosome pathway; FCERI mediated NF-kB activation; GSK3B-mediated proteasomal degradation of PD-L1(CD274); Interleukin-1 signaling; NIK-->noncanonical NF-kB signaling; SPOP-mediated proteasomal degradation of PD-L1(CD274); TNFR2 non-canonical NF-kB pathway
Cell Cycle: APC/C:Cdc20 mediated degradation of Securin; APC/C:Cdh1 mediated degradation of Cdc20 and other APC/C:Cdh1 targeted proteins in late mitosis/early G1; Autodegradation of Cdh1 by Cdh1:APC/C; Autodegradation of the E3 ubiquitin ligase COP1; Cdc20:Phospho-APC/C mediated degradation of Cyclin A; FBXL7 down-regulates AURKA during mitotic entry and in early mitosis; G2/M Checkpoints; SCF(Skp2)-mediated degradation of p27/p21; SCF-beta-TrCP mediated degradation of Emi1; Separation of Sister Chromatids; The role of GTSE1 in G2/M progression after G2 checkpoint; Ubiquitin-Mediated Degradation of Phosphorylated Cdc25A; Ubiquitin-dependent degradation of Cyclin D
Signal Transduction: Asymmetric localization of PCP proteins; Degradation of AXIN; Degradation of DVL; Degradation of GLI1 by the proteasome; Degradation of GLI2 by the proteasome; Degradation of beta-catenin by the destruction complex; GLI3 is processed to GLI3R by the proteasome; Hedgehog 'on' state; Hedgehog ligand biogenesis; MAPK6/MAPK4 signaling; Negative regulation of NOTCH4 signaling; Regulation of PTEN stability and activity; Regulation of RAS by GAPs
and 27 more pathways
Gene Ontology:
Molecular function: protein binding; proteasome-activating activity; ATP binding; ATP hydrolysis activity
Biological process: cellular response to type I interferon; proteasomal protein catabolic process; proteasome-mediated ubiquitin-dependent protein catabolic process; proteolysis; regulation of proteasomal protein catabolic process; response to oxidative stress
Cellular component: cytosol; membrane; nucleoplasm; nucleus; proteasome complex; proteasome accessory complex; synaptic vesicle; cytoplasm
Genetic constraint (gnomAD): Loss-of-function variants: 13 observed, 50.81 expected, observed/expected ratio (o/e) 0.26, 90% interval 0.17 to 0.41. The upper end of that interval is the gene's LOEUF score, 0.41, which puts it in group 1 of 6, group 1 being the genes least tolerant of losing a copy. Missense variants: 261 observed, 581.28 expected, observed/expected ratio (o/e) 0.45, 90% interval 0.41 to 0.5. Synonymous variants: 202 observed, 223.53 expected, observed/expected ratio (o/e) 0.9, 90% interval 0.81 to 1.01.
Homologues: Orthologues: dog PSMC4 (100% identical), macaque PSMC4 (100% identical), pig PSMC4 (100% identical), guinea pig PSMC4 (99% identical), mouse Psmc4 (99% identical), rat Psmc4 (99% identical), chimpanzee PSMC4 (97% identical), tropical clawed frog psmc4 (97% identical), zebrafish psmc4 (97% identical), Drosophila melanogaster Rpt3 (86% identical), Caenorhabditis elegans rpt-3 (77% identical), Drosophila melanogaster Rpt3R (76% identical). Paralogues in human: PSMC1 (47% identical), PSMC5 (43% identical), PSMC3 (40% identical), PSMC6 (38% identical), PSMC2 (36% identical).